ENSG00000305783 (novel transcript)
Synonyms: LOC102724892
Gene: Long non-coding RNA gene on chromosome 1 (84,770,982 to 84,797,774, reverse strand). Ensembl gene ENSG00000305783.
Diseases named in the same sentence as ENSG00000305783 in open-access papers:
ENSG00000305783 is named in the same sentence as 2 diseases in open-access papers, as found by Europe PMC text mining. Sharing a sentence is not in itself a finding about the gene and the disease.
ENSG00000305783 shares sentences with these, for which no sentence is quoted: hepatocellular carcinoma (1 paper); nasopharyngeal carcinoma (1).